TRIM22 (tripartite motif containing 22)
Description:
Interferon-induced E3 ubiquitin ligase that plays important roles in innate and adaptive immunity. Restricts the replication of many viruses including HIV-1, encephalomyocarditis virus (EMCV), hepatitis B virus (HBV), hepatitis C virus (HCV) or Zika virus (ZIKV). Mechanistically, negatively regulates HCV replication by promoting ubiquitination and subsequent degradation of viral NS5A. Also acts by promoting the degradation of Zika virus NS1 and NS3 proteins through proteasomal degradation. Acts as a suppressor of basal HIV-1 LTR-driven transcription by preventing Sp1 binding to the HIV-1 promoter. Also plays a role in antiviral immunity by co-regulating together with NT5C2 the RIGI/NF-kappa-B pathway by promoting 'Lys-63'-linked ubiquitination of RIGI, while NT5C2 is responsible for 'Lys-48'-linked ubiquitination of RIGI. Participates in adaptive immunity by suppressing the amount of MHC class II protein in a negative feedback manner in order to limit the extent of MHC class II induction.
Synonyms: RNF94; STAF50; GPSTAF50
Tractability: PROTAC: UniProt records ubiquitination sites on it; ubiquitination databases record sites on it; its protein half-life has been measured.
Gene: Protein-coding gene on chromosome 11 (5,689,610 to 5,737,089, forward strand). Ensembl gene ENSG00000132274.
Subcellular location: Cytoplasm; Nucleus; Nucleus speckle; Nucleus, Cajal body
Subcellular location (Human Protein Atlas): Nuclear bodies; Nucleoplasm; Golgi apparatus
Pathways (Reactome):
Immune System: Interferon gamma signaling
Gene Ontology:
Molecular function: identical protein binding; protein binding; protein kinase binding; protein-macromolecule adaptor activity; transcription coactivator activity; ubiquitin protein ligase activity; transcription corepressor activity; zinc ion binding
Biological process: positive regulation of autophagy; positive regulation of canonical NF-kappaB signal transduction; positive regulation of defense response to virus by host; protein K63-linked ubiquitination; regulation of protein localization; immune response; innate immune response; regulation of DNA-templated transcription; regulation of gene expression; response to virus; negative regulation of DNA-templated transcription; positive regulation of DNA-templated transcription; protein ubiquitination
Cellular component: cytoplasm; nuclear body; nucleoplasm; nucleus; cytosol; Cajal body; nuclear speck
Genetic constraint (gnomAD): Loss-of-function variants: 25 observed, 40.18 expected, observed/expected ratio (o/e) 0.62, 90% interval 0.45 to 0.87. The upper end of that interval is the gene's LOEUF score, 0.87, which puts it in group 3 of 6, group 1 being the genes least tolerant of losing a copy. Missense variants: 469 observed, 460.79 expected, observed/expected ratio (o/e) 1.02, 90% interval 0.94 to 1.1. Synonymous variants: 173 observed, 169 expected, observed/expected ratio (o/e) 1.02, 90% interval 0.9 to 1.16.
Homologues: Orthologues: chimpanzee TRIM22 (99% identical), macaque TRIM22 (92% identical), dog TRIM22 (66% identical), mouse Trim75 (29% identical). Paralogues in human: TRIM34 (58% identical), TRIM6 (56% identical), TRIM5 (53% identical), TRIM68 (34% identical), TRIM21 (32% identical), TRIM38 (31% identical), TRIM60 (27% identical), TRIM58 (27% identical), TRIM27 (26% identical), TRIM64 (26% identical), TRIM64B (26% identical), TRIM39 (26% identical), and 68 more.
Diseases named in the same sentence as TRIM22 in open-access papers:
TRIM22 is named in the same sentence as 76 diseases in open-access papers, as found by Europe PMC text mining. Sharing a sentence is not in itself a finding about the gene and the disease. The quoted sentences say what the papers report.
viral infection (24 papers, 2014 to 2025). "Loss of TRIM22 function led to reduced production of type I interferons (IFNs) in response to viral infection such as influenza A virus (IAV) or vesicular stomatitis virus (VSV), thereby facilitating viral replication." (PMID 40162781, 2025). "Single nucleotide polymorphisms (SNPs) at TRIM5 and TRIM22 genes have shown to influence several viral infections such as human immunodeficiency virus (HIV), hepatitis B, as well as measles and rubella vaccination." (PMID 27590274, 2016). "Moreover, SNPs on TRIM22 have been associated with several aspects of viral infections such as chronic hepatitis B infection, HIV replication, and specific antibody and cytokine levels after vaccination against measles and rubella." (PMID 36028902, 2022). "The function and pathway enrichment analyses of M. tuberculosis H37Rv-infected macrophage by RNA-seq demonstrated that gene enrichment was closely associated with viral infection genes, including TRIM22, IFIT1, IFI44L, and IFI44, consistent with M. tuberculosis being an intracellular pathogen." (PMID 34722780, 2021). "In this loop, ELF3 rapidly translocates to the nucleus to activate TRIM22 gene expression after viral infection, while TRIM22 activates IFN-β antiviral signaling through K63-linked polyubiquitination of MAVS." (PMID 40162781, 2025). "In our study, we explored the important role of TRIM22, a protein that helped regulate the host’s immune response to viral infections." (PMID 40162781, 2025). "Our results suggest that the degradation of NSP8 mediated by TRIM22, an interferon-stimulated gene, sheds light on the intricate mechanisms employed by the host immune system to combat viral infections." (PMID 38275298, 2024). "One possible reason for this is that the diversification of TRIM5 was sufficient to counteract the variety of viral diseases in most mammals, and, therefore, the same process happening in TRIM22 would be evolutionarily redundant." (PMID 35215944, 2022). "Using primary cell lines of lung origin and the airways of rhesus macaques, we show the constitutive expression of TRIM22 to occur independently of interferon-stimulation or viral infection." (PMID 34621686, 2021). "As we had identified TRIM22 to be amongst the top 50 constitutively expressed ISGs in the lung, we next analysed how TRIM22 expression in the respiratory tract responded to viral infection." (PMID 34621686, 2021). "The high levels of constitutive TRIM22 expression was surprising, since this level of expression has been previously reported to require viral infection or IFN stimulation." (PMID 34621686, 2021). "As in other tissues, TRIM22 is constitutively expressed in epithelial cells, but it is promptly induced by viral infection." (PMID 34440633, 2021). "For example, TRIM22 is upregulated during viral infection and significantly inhibits the replication of AIV." (PMID 34516573, 2021). "Accordingly, TRIM22 has been shown to inhibit viral infection following its induced expression as an ISG by restricting the onset of viral transcription or targeted degradation of viral proteins." (PMID 34621686, 2021). "By using primary cell lines and the airways of rhesus macaques, we show the interferon-stimulated antiviral effector protein TRIM22 (TRIpartite Motif 22) to be constitutively expressed in the lung independently of viral infection or innate immune stimulation." (PMID 34621686, 2021). "Our finding that TRIM22 is one of the most abundantly expressed TRIM proteins in lung tissue came as a surprise, as the expression of TRIM22 has been widely reported to require viral infection or immune stimulation in multiple cell culture model systems." (PMID 34621686, 2021). "Secreted IFN-α/β bind to IFNAR to activate the Stat1–Stat2 heterodimer and induce expression of TRIM22, thereby protecting the host against diverse viral infections." (PMID 34068322, 2021).
viral infection (continued). "Interferon signalling is essential for the production of anti-viral mediators (such as OAS1, Mx1, SP100, and TRIM22) to defend against virus infection." (PMID 28273165, 2017). "TRIM22 SNPs have been related to several aspects of viral infections such as HIV replication, chronic hepatitis B infection, and levels of specific antibodies and cytokines following measles and rubella vaccination." (PMID 27590274, 2016). "TRIM22 is endowed with a potent capacity to repress various viral infections, including HIV28, HBV16,29, EMCV30, and IAV17." (PMID 27667714, 2016). "TRIM6 and TRIM22 have both been reported to drive innate immune responses to viral infection." (PMID 40216791, 2025). "As a member of the TRIM family, TRIM22 regulates viral infection through various mechanisms." (PMID 36587218, 2022). "Furthermore, SNPs in TRIM22 are involved in several aspects of viral infections, including the replication of HIV, HBV infection, and HCV infection." (PMID 36028902, 2022). "Our observation that constitutive TRIM22 also restricts the spread of virus infection suggests that this pre-existing defence may also play a valuable role in slowing down the rate of IAV replication prior to activation of additional host defences." (PMID 34621686, 2021). "Although TRIM22 depletion did not significantly change the levels of euchromatin marks on ICP27 and ICP4 promoters, there was a trend towards increased density of H3K9Ac immunoprecipitated on the ICP27 promoter in 7134 and 7134R virus infection under conditions of TRIM22 depletion." (PMID 33524065, 2021). "TRIM22 is one of these genes that contributes to limiting viral infection." (PMID 34440633, 2021). "As shown, TRIM22 enhanced the ubiquitination of MAVS following IAV-H1N1 or H3N2 infection, whereas TRIM22 knockdown reduced the ubiquitination levels of MAVS, underscoring the critical role of TRIM22 in viral infection." (PMID 40162781, 2025). "Our experiments revealed that viral infection promoted the nuclear translocation of ELF3, a member of the ETS transcription factor family, thereby enhancing TRIM22 expression and contributing to its antiviral effects." (PMID 40162781, 2025). "These antiviral genes involved in the innate immune response as part of the host defence response to clear viral infections were specifically upregulated, including IFI44L and TRIM22 in M. tuberculosis-infected macrophages." (PMID 34722780, 2021). "TRIM22 depletion significantly reduced the total histone H3 immunoprecipitated on the viral ICP27 and ICP4 gene promoters in the 7134 virus infection." (PMID 33524065, 2021). "Among these, the expression of Mx1, Mx2, TRIM22, WARS, ISG15, ISG20, UBA7, DDX58, and OAS1-3 were up-regulated, representing an increased innate immune response against viral infections." (PMID 25883591, 2015). "Most overexpressed proteins are involved in immune response, as T-cells activation and functions (CD59, IL12A) or the response to bacterial and viral infections (CTSD, TRIM22)." (PMID 25594007, 2014). "To explore whether TRIM22 modulates MAVS ubiquitination under viral infection conditions, we employed IAV-infected cells with either overexpression or knockdown of TRIM22." (PMID 40162781, 2025). "The MX, TRIM22, ISG15, OAS, and SFTPA1, B gene are important effectors of innate immune response against viral infections." (PMID 25883591, 2015). "However, some of these proteins also are involved in immune response and inflammation, as T-cells function and activation (CD59, IL12A); others are involved in the response to bacterial and viral infections (CTSD, TRIM22)." (PMID 25594007, 2014). "Expression changes in UPS genes identified in both ST_EPN_RELA and PF_EPN_B included several differentially expressed UPS genes associated with interferon gamma signaling (MID1, PIAS1, TRIM2, TRIM22, TRIM45) that may promote a proinflammatory milieu similar to that observed upon viral infections." (PMID 36293188, 2022).
viral infection (continued). "In addition, TRIM22 depletion reduced the density of H3K9me3 and H3K27me3 immunoprecipitated on the ICP27 and ICP4 promoters in the 7134 virus infection, indicating that the viral DNA is not silenced to the same extent in TRIM22-depleted fibroblasts." (PMID 33524065, 2021).
osteosarcoma (17 papers, 2021 to 2025). A usually aggressive malignant bone-forming mesenchymal neoplasm, predominantly affecting adolescents and young adults. "TRIM22 has been implicated in regulating the progression and development of various cancers, including glioblastoma, osteosarcoma, and gastric cancer." (PMID 38199981, 2024). "In contrast, TRIM22 is upregulated in glioblastoma, where it promotes tumor proliferation, while the upregulation of TRIM22 in osteosarcoma suppresses progression by destabilizing NRF2 and activating the ROS/AMPK/mTOR/autophagy signaling pathway." (PMID 40075566, 2025). "Overall, TRIM22 promotes autophagic osteosarcoma cell death and inhibits osteosarcoma progression by promoting NRF2 proteasomal degradation, activating the ROS/AMPK/mTOR/autophagy signaling." (PMID 39062505, 2024). "For example, in osteosarcoma, TRIM22 can impact autophagy by modulating the ROS/AMPK/mTOR signaling pathway, while in lung cancer, it can influence epithelial‐mesenchymal transition through the AKT/GSK3β signaling pathway." (PMID 38468469, 2024). "In vitro and in vivo functional evidence suggests that TRIM22 inhibits osteosarcoma cell proliferation and metastasis." (PMID 39062505, 2024). "For instance, TRIM22 has been shown to inhibit osteosarcoma progression by activating the ROS/AMPK/mTOR/autophagy signaling pathway through weakening Nrf2 protein stability." (PMID 39667820, 2024). "Functional experiments demonstrate that partial knockout of NRF2 reverses the pro-progression effect of TRIM22 knockout in osteosarcoma." (PMID 39062505, 2024). "In osteosarcoma, TRIM22 has been observed to promote Keap1-independent degradation of Nrf2, thereby activating autophagy signaling pathways and ultimately impeding osteosarcoma progression." (PMID 39664581, 2024). "Up‐regulation of TRIM22, which is down‐regulated in osteosarcoma, plays a tumor‐suppressive role by reducing the proliferation and metastasis of osteosarcoma cells." (PMID 39667820, 2024). "Previous studies have reported that TRIM22 induces apoptosis in osteosarcoma, monocyte, and neuron cells." (PMID 38199981, 2024). "Autophagy activation is observed in osteosarcoma cells overexpressing TRIM22, leading to autophagic cell death." (PMID 39062505, 2024). "TRIM22, not only an ubiquitin E3 ligase but also an interferon-induced protein, has been established to be both nuclear and cytoplasmic in the human osteosarcoma cell line U2OS." (PMID 39062505, 2024). "TRIM22 inhibits osteosarcoma development by aggravating proteasomal degradation of NRF2 to motivate ROS/AMPK/mTOR/autophagy signaling, which results in autophagic cell death in osteosarcoma." (PMID 36870986, 2023). "TRIM22 inhibits osteosarcoma progression by destroying NRF2 and activating ROS/AMPK/mTOR/autophagy signalling." (PMID 38037161, 2023). "For instance, TRIM22 was found to inhibit osteosarcoma progression via destabilizing NRF2, which subsequently resulted in the imbalance of intracellular reactive oxygen species (ROS) and further activation of AMPK/mTOR/autophagy signaling." (PMID 37591850, 2023). "In osteosarcoma, TRIM22 can interact with Nrf2 and accelerate its degradation by inducing ubiquitination dependent on its E3 ligase activity, thus activating downstream AMPK/mTOR signaling, and affecting Nrf2-mediated ROS imbalance." (PMID 36261847, 2022). "In osteosarcoma, TRIM22 inhibits tumor progression via ROS/AMPK/mTOR-mediated autophagy activation." (PMID 40758712, 2025). "Conversely, TRIM22 is downregulated in osteosarcoma (OS) and gastric cancer." (PMID 38199981, 2024). "This suggests that the TRIM22/Nrf2/autophagy signaling axis may represent a promising therapeutic target for osteosarcoma treatment." (PMID 39664581, 2024). "Moreover, TRIM22 can inhibit the Warburg effect in osteosarcoma cells." (PMID 39062505, 2024). "This indicates that the TRIM22/NRF2 pathway could be a promising target for osteosarcoma treatment." (PMID 39211390, 2024).
osteosarcoma (continued). "Moreover, TRIM22 was found to inhibit the Warburg effect in osteosarcoma cells." (PMID 36261847, 2022). "TRIM22 inhibites osteosarcoma progression by promoting proteasomal degradation of NRF2 independent of KEAP1, thereby activating AMPK/mTOR/autophagy signaling that led to autophagic osteosarcoma cell death." (PMID 36261847, 2022). "However, a significantly negative correlation was found between TNFAIP8L1, TRIM22, and other genes proven to inhibit osteosarcoma metastasis." (PMID 37190333, 2023). "However, NRF2 can be ubiquitinated for degradation also by other E3 ligases such as TRIM22, which accelerates the ubiquitination and proteasomal degradation of NRF2 and increases autophagy but independently of KEAP1 activity, as seen in in vitro experiments on osteosarcoma." (PMID 38534381, 2024).
HIV-1 infection (14 papers, 2011 to 2024). The type species of lentivirus and the etiologic agent of acquired immunodeficiency syndrome (AIDS). "Regarding TRIM22, two SNPs have been correlated with in vitro HIV-1 infection and the severity of the disease." (PMID 34440633, 2021). "They provided the first evidence that TRIM22 can restrict HIV-1 replication in vitro by showing that exogenous expression of TRIM22 inhibited HIV-1 infection by 50–90% in 293T cells modified to express the CD4 and CCR5 receptors and in primary MDM." (PMID 22649727, 2012). "Recently, TRIM22 has been shown to be a correlate of HIV-1 infection and can block HIV-1 Gag particle production by altering intracellular trafficking of Gag to the plasma membrane and by inhibiting transcription from the HIV-1 long terminal repeat." (PMID 22093708, 2011). "The different susceptibility to HIV-1 infection in U937 cells—permissive (Plus) or nonpermissive (Minus)—is linked to the expression in Minus cells of interferon (IFN)-γ inducible antiviral factors such as tripartite motif-containing protein 22 (TRIM22) and class II transactivator (CIITA)." (PMID 39205150, 2024). "TRIM22 inhibits basic HIV-1 transcription by preventing Sp1 from binding to the HIV-1 promoter, thus inhibiting HIV-1 infection." (PMID 36587218, 2022). "It is first identified that TRIM22 is an interferon- (IFN-) inducible protein, which plays a role in HIV-1 infection." (PMID 33299853, 2020). "They found that persistent HIV-1 infection in humanized-mice led to induction of IFNs and ISGs including MX2, IFITM3, Trim22, ISG15, OAS1, and IFN regulatory factor 7 (IRF7) both in peripheral blood mononuclear cells (PBMCs) and in the spleen." (PMID 30665429, 2019). "In this regard, the overexpression of TRIM22 negatively correlated with HCV viral load and HIV-1 viral load, while gene silencing of TRIM22 enhanced HIV-1 infection of target cells." (PMID 27590274, 2016). "Collectively, TRIM22 is a key inhibitor of HIV-1 infection after IFN treatment, but TRIM22 may also inhibit other viruses, including the enveloped DNA virus HBV and the nonenveloped picornavirus EMCV." (PMID 23435233, 2013). "We previously found that the different susceptibility to HIV-1 infection in the two isogenic promonocytic U937 cell Minus and Plus clones was associated with the expression of both CIITA and TRIM22 restriction factors in Minus cells but not in HIV-1 permissive Plus cells." (PMID 39205150, 2024).